BRCA1 (BRCA1 DNA repair associated)
Diseases named in the same sentence as BRCA1 in open-access papers (continued):
Sharing a sentence is not in itself a finding about the gene and the disease.
Hereditary breast and ovarian cancer syndrome (continued). "Here, we performed comprehensive genetic testing of BRs to identify any PGV from among 30 causative genes associated with HBOC syndrome, regardless of PGV positivity status of the BRCA1/BRCA2 wild-type proband." (PMID 39003386, 2024). "All patients met the clinical criteria for hereditary breast and ovarian cancer syndrome (HBOC) and were negative for BRCA1 and BRCA2 mutations." (PMID 35625568, 2022). "In the last decade, advances in sequencing methods have revealed a marked heterogeneity in the loci related to hereditary breast and ovarian cancer (HBOC), with more than 25 genes emerging, most of which are involved in maintenance and repair genome pathways connected with BRCA1/2." (PMID 34204722, 2021). "Although this ancestry is associated with an increased risk of a pathogenic genetic variant in BRCA1/BRCA2, it is not the only pathogenic variant associated with Hereditary Breast and Ovarian Cancer Syndrome despite the emphasis it receives in practice guidelines." (PMID 37626335, 2023). "BRCA phenocopies are individuals with the same phenotype (i.e. cancer consistent with Hereditary Breast and Ovarian Cancer syndrome = HBOC) as their affected relatives, but not the same genotype as assessed by blood germline testing (i.e. they do not carry a germline BRCA1 or BRCA2 mutation)." (PMID 31346352, 2019). "However, other than germline BRCA1 or BRCA2 mutations, which are related to hereditary breast-ovarian cancer (HBOC), cancer-predisposition genes have not been well studied in this population." (PMID 28961279, 2017). "Overall, 8 distinct BRCA1 and 5 distinct BRCA2 pathogenic mutations were found in 35 (10%) out of 348 breast-ovarian cancer families; 11 "high-risk" families were positive for BRCA1 and 12 for BRCA2, whereas 1 BRCA1 and 11 BRCA2 mutations were identified in "no high-risk" families." (PMID 19619314, 2009). "We provide evidence of the existence of free methylated nucleotides capable of distinguishing plasma samples from HBOC patients as BRCA1-mutated and BRCA1 non-mutated, suggesting that they might be considered as BRCA1-like biomarkers for TNBC and HBOC syndrome." (PMID 29259228, 2017). "However, recommendations regarding genetic testing other than BRCA1 and BRCA2 continue to vary between countries, and the data and testing policy of non-BRCA genes among Thai patients with the hereditary breast-ovarian cancer (HBOC) spectrum remains insufficient." (PMID 38355628, 2024).
Fanconi anemia (201 papers, 2004 to 2026). Fanconi anemia (FA) is a hereditary DNA repair disorder characterized by progressive pancytopenia with bone marrow failure, variable congenital malformations and predisposition to develop hematological or solid tumors. "A BRCA1 mutation in a homozygous state is causative of Fanconi anemia (MIM #617883); otherwise, cancer predisposition is related to a single mutated allele." (PMID 40725177, 2025). "Reports of dual carriers of pathogenic BRCA1 variants in trans are extremely rare, and so far, most individuals have been associated with a Fanconi Anemia-like phenotype." (PMID 38195559, 2024). "Subsequently, several studies have found that mutations in other genes besides BRCA1/2 can also result in BRCAness, including HR-related genes, DNA damage signaling genes, and Fanconi-anemia-related genes." (PMID 38745917, 2024). "Dysfunction of BRCA1 and FA factors is associated with breast cancer and Fanconi anemia, respectively." (PMID 36428700, 2022). "For example, BRCA1 mutations have been linked to Fanconi anemia (FA), an inherited BM failure syndrome with hematopoietic phenotypes such as myelodysplastic syndrome, cytopenia, and acute myeloid leukemia (AML), since BRCA1 interacts with several FA proteins." (PMID 36346676, 2022). "HRD is an emerging biomarker defined by the mutations of BRCA1/2 genes, along with other Fanconi anemia pathway genes (RAD51D, NBN, and ATM)." (PMID 35983074, 2022). "Among the 22 FA or FA-like genes, BRCA1 is considered as FANCS (Fanconi anemia gene), homozygous mutations of the BRCA1 gene contributed to FA group S." (PMID 33477375, 2021). "This framework is equally relevant for BRCA1/2 bi-allelic mutations, such as those observed in Fanconi anemia patients." (PMID 34359619, 2021). "Despite BRCA1 biallelic pathogenic mutations being extremely rare, they have been reported to be embryonically lethal or to cause Fanconi anemia (FA)." (PMID 33477375, 2021). "Another classic example is Fanconi anemia as a result of biallelic BRCA1/2 mutations (OMIM PS227650)." (PMID 38836198, 2021). "BRCA1 biallelic pathogenic mutations are extremely rare, which are regarded as embryonically lethal or causing Fanconi anemia (FA)." (PMID 33477375, 2021). "***: A carrier state for an ultra-rare autosomal-recessive disorder which corresponds to an autosomal-dominant hereditary disease (e. g., BRCA1-associated tumor predisposition/Fanconi anemia)." (PMID 38836198, 2021). "The BRCA1 (FANCS) mutation is the best known example of a mutation in the Fanconi Anaemia (FA)/DNA damage repair pathway." (PMID 34880407, 2021). "The study revealed a high rate of inherited variants in patients of young ages with a wide spectrum of variants along the Fanconi anemia pathway (BRCA1, BRCA2, and PALB2)." (PMID 33646313, 2021). "By doing so MAD2L2 affects the development and treatment of human disease, such as Fanconi Anemia and cancer, in which it determines the sensitivity of BRCA1-deficient cancers to treatment with Parp inhibitors." (PMID 34521823, 2021). "Biallelic PALB2 pathogenic variants were showed to cause Fanconi anemia, similar to BRCA1 and BRCA225." (PMID 31937788, 2020). "BRCA1 is encoded by the BRCA1 gene, which is known to cause hereditary breast and ovarian cancer syndrome and Fanconi anemia." (PMID 31861888, 2019). "Microarray analysis and real-time quantitative PCR demonstrated downregulation of genes associated with Fanconi anemia (BRCA1 and BRCA2) and 28 driver oncogenes." (PMID 30719229, 2019). "qRT-PCR data confirmed that the expression of Fanconi anemia-associated genes including BRCA1, BRCA2, PALB2, and RAD51 and cancer-associated genes (ALDH1A3 and IGF1R) was strongly inhibited by FR treatment, as shown by microarray analysis." (PMID 30719229, 2019).
Fanconi anemia (continued). "Biallelic BRCA1 mutations are regarded either embryonically lethal or to cause Fanconi anemia (FA), a genomic instability syndrome characterized by bone marrow failure, developmental abnormalities, and cancer predisposition." (PMID 31347298, 2019). "FANCF (Fanconi anemia, complementation group M) is a gene associated with Fanconi anemia, the protein products of which were reported to interact with proteins involved in DNA repair pathways, e.g., with BRCA1." (PMID 35582723, 2019). "Proteins other than BRCA2 implicated in homologous recombination or the Fanconi anemia repair pathway, like BRCA1, RAD51, PALB2, XRCC3, FANCI, or FANCD2, were at most modestly affected, as were non-homologous end joining proteins like KU80, KU70, and XRCC4." (PMID 28575672, 2017). "Cells derived from Fanconi anemia (FA) patients or BRCA1/2-associated tumors that lack the BRCA-FA pathway (BRCA-FA cells) are extremely sensitive to agents such as mitomycin C (MMC) that induce ICLs." (PMID 24966277, 2014). "At stalled replication forks in human cells, DNA-end processing or end protection by Mre11 depends on protein partners, including breast cancer type 2 susceptibility protein (BRCA2) and Fanconi anemia (FA) proteins BRCA1 and FANCD1." (PMID 24062528, 2013). "Biallelic loss-of-function mutations of BRCA1 result in Fanconi anemia, complementation group S." (PMID 40519304, 2025). "However, the authors assumed that the biallelic BRCA1 variants caused phenotypical differences and developmental delay in the patient, which they diagnosed as a “Fanconi Anemia (FA)-like phenotype”." (PMID 38195559, 2024). "However, there have now been a number of individual case reports of biallelic pathogenic BRCA1 mutations, many of whom have been identified as having a new form of Fanconi Anaemia – FA-S." (PMID 38146508, 2023). "However, given its strong associations with both Fanconi anaemia and homologous recombination repair, and the observation that it is embryonically lethal (like BRCA1 and BRCA2), this places C1ORF112 in the downstream stretch of the FA pathway." (PMID 33625522, 2021). "Inherited defects in DNA repair pathways, such as germline mutations in BRCA1 or Fanconi anemia pathway genes that normally repair double‐strand breaks and DNA cross‐links, lead to the accumulation of mutations that impair stem cell function and promote tumorigenesis." (PMID 33660437, 2021). "In sporadic cases, homozygous BRCA1 mutations lead to Fanconi anemia with microcephaly." (PMID 33441416, 2021). "Accordingly, downregulation of BRCA1 and Fanconi anemia pathway in TIGAR-deficient cells may provide a molecular mechanism attributable to the increased sensitivity to olaparib after TIGAR KD in cancer cells." (PMID 31508509, 2019). "We next tested whether the QIBC-based PARPi-DDR approach could faithfully recapitulate known clinically relevant mechanisms of PARPi sensitivity, specifically loss of BRCA1/21,2 and Fanconi anemia (FA) genes." (PMID 29992957, 2018). "Approximately 40-50% of HGSOC have some level of genetic or epigenetic alterations in HR repair pathways including mutations in BRCA1/2, Fanconi anemia genes, core HR genes, DNA damage response genes and epigenetic silencing of BRCA1 via promoter hypermethylation." (PMID 30647846, 2018). "Additionally, we found 7 monoallelic pathogenic variants (2%, 7/327) in 6 genes (besides BRCA1/2) of the interstrand crosslink DNA repair Fanconi anemia pathway (FANCB, FANCC, FANCF, FANCI, FANCL, FANCM) and 1 in RAD51C, a Fanconi-like phenotype gene." (PMID 30262796, 2018). "Homozygous germ line mutations in BRCA1 can result in a Fanconi anemia-like phenotype, BRCA1 may thus be considered an FA-like gene whose action may thus be closely connected to the FA pathway." (PMID 25161863, 2014).
Fanconi anemia (continued). "Silencing of BRCA1, through promoter methylation, decreased expression through gene deletion (loss of heterozygosity), or dysregulation of related genes in the Fanconi anemia/BRCA1 pathway, is believed to be important in the pathogenesis of a significant proportion of sporadic tumors." (PMID 21854619, 2011). "It is unclear at this stage whether the remaining seven MMC responsive genes play a role in the Fanconi anemia pathway, and how they are functionally linked to BRCA1 and/or BRCA2." (PMID 20174566, 2010). "BRCA1 could also be associated with the DNA repair activities of the Fanconi anemia (FA) pathway (see next section), as both physical and functional interactions between BRCA1 and FA complex proteins in response to DNA damage have been described." (PMID 19007437, 2008). "Monoallelic germline pathogenic variants (GPVs) in five Fanconi anemia (FA) genes (BRCA1/FANCS, BRCA2/FANCD1, PALB2/FANCN, BRIP1/FANCJ, and RAD51C/FANCO) confer an increased risk of breast (BC) and/or ovarian (OC) cancer, but the role of GPVs in 17 other FA genes remains unclear." (PMID 39149814, 2024). "Fortunately, the biallelic presence of pathogenic BRCA2 alleles is associated with a specific fully penetrant clinical phenotype known as Fanconi anemia and may present as microcephalic primordial dwarfism in severe cases, whereas biallelic BRCA1 mutation is presumably lethal in humans." (PMID 27884173, 2016). "P/LP germline variants were recurrent in homologous recombination (n = 9; BRCA1, BRCA2, PALB2) and Fanconi anemia genes (n = 4)." (PMID 40072012, 2025). "FANCG, together with established breast/ovarian predisposition genes BRCA1 and BRCA2 belongs to the Fanconi anemia gene family; however, little is known about cancer predisposition in carriers of FANCG germline alterations." (PMID 39149814, 2024). "The results pinpoint a minimum necessary BRCA1 protein activity to avoid a Fanconi Anemia-like phenotype in compound heterozygous status and yet still predispose carriers to hormone-related cancers." (PMID 38195559, 2024). "Fanconi Anemia is, in fact, related to different DNA repair gene mutations, known as FANC genes, with FANCS and FANCD1 corresponding, respectively, to BRCA1 and BRCA2." (PMID 38792636, 2024). "The BRCA1/2 proteins function in the homologous recombination (HR) mediated repair of DNA double-strand breaks (DSBs), and are a key component of the Fanconi anaemia (FA) pathway which repairs DNA interstrand crosslinks (ICLs) induced by platinum treatment." (PMID 38711848, 2024). "BRIP1 is a member of the Fanconi Anaemia gene family and functions in the double-strand break repair pathway, interacting closely with BRCA1." (PMID 39001544, 2024). "In CRC, significant associations of HR (BRCA1, BRCA2, BARD1, PALB2 and BRIP1) and Fanconi anaemia (FANCA, FANCC and FANCG) genes with TMB were identified." (PMID 37821580, 2023). "BRCA1 is involved in the Fanconi anaemia (FA) pathway, which coordinates repair of DNA interstrand cross-links." (PMID 38146508, 2023). "BRIP1 (BRCA1 interacting helicase 1), also known as FANCJ (as the gene mutated in the J complementation group of Fanconi anemia) or BACH1 (BRCA1-associated C-terminal helicase), was first discovered in 2001 by its interaction with BRCA1." (PMID 37153833, 2023). "BRCA1 and the Fanconi anemia (FA) pathway factors FANCA, FANCD2, and TOP1 have been reported to bind R-loop during DNA damage repair." (PMID 36428700, 2022). "During the S-phase, interstrand crosslinks can be repaired through the Fanconi anaemia pathway followed by a homologous recombination, where BRCA1/2 are important players." (PMID 36230472, 2022). "In particular, treatment with bortezomib reduced the levels of Fanconi Anemia (FA) factors BRCA1/2 and FANCD2, and proved effective to induce DNA damage and cell death in combination with melphalan." (PMID 36569948, 2022).
Fanconi anemia (continued). "KEGG pathway analysis displayed that BRCA1/2 co-expressed genes were enriched in regulating the cell cycle, RNA transport, and the Fanconi anemia pathway." (PMID 35409110, 2022). "On average, samples with somatic mutations in BRCA1, BRCA2, PTEN, or somatic mutations or gene deletions in any gene belonging to the Fanconi Anemia (FA) or HR pathways showed high ovaHRDscar levels." (PMID 36581696, 2022). "Diverse mechanisms can cause defective BRCA‐like behavior, including inherited mutations in BRCA1, BRCA2, and Fanconi anemia complementation (FANC) group of genes." (PMID 33660437, 2021). "Fanconi Anemia (FA) genes were mutated in 152 patients, with BRCA2 (4.0%), BRCA1 (3.7%), and BRIP1 (2.8%) mutations occurring most frequently." (PMID 34620846, 2021). "This occurs in part via a Wnt/β‐catenin pathway acting in part through MYBL2, that enhances the expression of genes involved in homologous recombination and Fanconi anemia pathways, including BRCA1, BRCA2 and multiple FANC genes." (PMID 33660437, 2021). "BRIP1, which belongs to the Fanconi anemia (FA) gene family, was first identified via tandem mass spectrometry through its physical interaction with BRCA1." (PMID 34408776, 2021). "Overall, 14.6% had mutations in BRCA1 or BRCA2, 3.3% had mutations in other BRCA–Fanconi anemia genes (BRIP1, PALB2, RAD51C, RAD51D, BARD1), and 0.4% had mutations in mismatch repair genes linked to Lynch syndrome." (PMID 32679669, 2020). "First, we provide a brief history of BRCA1 and BRCA2, including their identification as cancer predisposition genes and recognition as members in the Fanconi anemia pathway." (PMID 32269964, 2020). "Similar to BRCA1 mutants, KO mice of several Fanconi anemia complementation group proteins are viable but have HR defects." (PMID 32139898, 2020). "TIGAR knockdown enhances sensitivity to olaparib in cancer cells via downregulation of BRCA1 and the Fanconi anemia pathway and increases senescence of these cells by affecting metabolic pathways and increasing the cytotoxic effects of olaparib." (PMID 31508509, 2019). "In line with this key observation, FANCF, another member of the BRCA1/Fanconi anemia pathway, was also hypermethylated." (PMID 30683142, 2019). "The associations involving DNA double-strand break repair pathway and Fanconi anemia, in particular, were also evident when examining key individual genes, including BRCA1, BRCA2, FANCD2, FANCI, and RAD51." (PMID 31610796, 2019). "Of these, about one-quarter (6% of all ovarian, fallopian tube, and peritoneal cancers) are caused by genes other than BRCA1 and BRCA2, including many genes associated with the Fanconi anemia pathway or otherwise involved with homologous recombination." (PMID 30650666, 2019). "Activated FANCD2 as well as BRCA1 regulate the DNA repair by homologous recombination and are therefore critical for the function of the Fanconi anemia pathway." (PMID 30400780, 2018). "FANCD2 belongs to the Fanconi anemia pathway and is involved in the DNA damage response by cooperating with BRCA1/2 proteins in homologous-recombination (HR)-mediated repair." (PMID 30038706, 2018). "BRIP1 (BRCA1 interacting protein C-terminal helicase 1) is a protein that works with BRCA1 to repair damaged DNA and the inheritance of two mutated copies of BRIP1 causes Fanconi anaemia." (PMID 30353044, 2018). "BRCA1 promotes fork cleavage/unhooking at the initiation step of the Fanconi anemia pathway, in which replication forks are blocked by DNA interstrand crosslinks." (PMID 29106372, 2017). "Evaluation of tumor tissue found additional somatic mutations in BRCA1/2 (3%), EMSY (8%), PTEN (7%), RAD51C (3%), ATM/ATR (2%) and Fanconi anemia genes (5%)." (PMID 28250960, 2017). "We also find that 18 VOUS BRCA1 and BRCA2 variants that are listed in BRCA Exchange are present at least once in the homozygous state in patients who lack features of Fanconi anemia." (PMID 27884173, 2016).